GAD1 (glutamate decarboxylase 1)
Diseases named in the same sentence as GAD1 in open-access papers (continued):
Sharing a sentence is not in itself a finding about the gene and the disease.
metabolic disease (1 paper, 2013). A congenital disorder (due to inherited enzyme abnormality) or acquired (due to failure of a metabolically important organ) disorder resulting from an abnormal metabolic process. "GAD2 is localized to the nerve terminal and is reversibly bound to the membrane of synaptic vesicles, which has been linked with lower birth weights and additional risk for metabolic diseases, whereas GAD1 is a cytosolic enzyme distributed throughout the organs and central nervous system." (PMID 24261884, 2013).
GAD1 also shares sentences with these, for which no sentence is quoted: stiff-person syndrome (67 papers); Autoimmunity (40); encephalitis (25); autoimmune encephalitis (22); bipolar disorder (20); type 2 diabetes (17); Hyperglycemia (14); Ataxia (13); temporal lobe epilepsy (13); autoimmune disease (12); mood disorder (12); Hypertension (7); insomnia (7); COVID-19 (6); myasthenia gravis (6); Parkinsonism (6); autoimmune thyroid disease (5); dementia (5); diabetic ketoacidosis (5); insulinoma (5); Miller Fisher syndrome (5); thyroid disorders (5); viral infection (5); celiac disease (4); Cerebellar atrophy (4); deafness (4); focal epilepsy (4); Hashimoto’s encephalopathy (4); hearing loss (4); MODY (4).
A further 143 diseases each share a sentence with GAD1 in 4 papers or fewer.